MMP9 (matrix metallopeptidase 9)
Diseases named in the same sentence as MMP9 in open-access papers (continued):
Sharing a sentence is not in itself a finding about the gene and the disease.
atherosclerosis (continued). "The previous study demonstrated an increased risk of severe atherosclerosis and unstable plaques in patients with higher MMP-9 levels." (PMID 26965176, 2016). "Recent studies have shown that MMP-9, an endopeptidase capable of degrading the extracellular matrix, is thought to be particularly associated with atherosclerosis and plaque rupture." (PMID 27298828, 2016). "The association between MMP-2 and TIMP-1 with atherosclerosis was the most frequently assessed (four studies) with MMP-9 also assessed in three." (PMID 27042350, 2016). "We also assessed correlations of sAF with traditional and “new” atherosclerosis risk factors, such as the cIMT and the concentration of markers of inflammation and/or endothelial damage, including sE-selectin, MMP-9, TIMP-1, ADMA, SDMA and PAI-1." (PMID 25409659, 2015). "MMPs have been implicated in the progression of atherosclerosis and plaque rupture, and MMP-9 was strongly correlated with plaque instability." (PMID 25007151, 2014). "In this study we tried to find correlations of three MMP polymorphisms (–1607 1G/2G MMP1; –1612 5A/6A MMP3; –1562 C/T MMP9) with a higher risk of myocardial infarction and formation of atherosclerosis plaque." (PMID 23274712, 2013). "Increased expression of MMP-9 is implicated in many pathological conditions including metastatic cancer, multiple sclerosis, and atherosclerosis." (PMID 22879913, 2012). "In one study of 473 subjects, blood levels of MMP-9 were associated with grade of atherosclerosis in the femoral artery." (PMID 21698093, 2011). "An association of MMP9 levels with atherosclerotic changes has been previously found in patients with atherosclerosis of the femoral artery and with chronic periodontitis." (PMID 20037727, 2009). "Elevated MMP-9 concentrations have been associated with the development of atherosclerosis." (PMID 41503448, 2026). "Animal experiments also demonstrate the association between MMP9 and atherosclerosis." (PMID 40356625, 2025). "Additionally, MMP-2 and MMP-9 are linked to inflammatory responses (GO:0006954) and are highly expressed in chronic inflammatory conditions such as rheumatoid arthritis and atherosclerosis." (PMID 40868841, 2025). "NINJ1 and MMP9 are closely associated with the occurrence and progression of atherosclerosis." (PMID 40356625, 2025). "Furthermore, studies suggest that at high levels, there are reports that pro-inflammatory and atherosclerosis signaling factors, including MMP-9, were associated with a significantly higher risk of adverse clinical outcomes." (PMID 37371326, 2023). "Genetic variants of MMP-9 were found to be associated with different stages of atherosclerosis." (PMID 32486345, 2020). "Additionally, a genetic variant in the promoter of human MMP-9 that leads to this increased expression was found to be associated with more severe atherosclerosis." (PMID 31067818, 2019). "This study validated this hypothesis and established a detailed mechanism underlying LPA on MMP-9 expression in macrophages and provided a new perspective for the progression of atherosclerosis plaque destabilization." (PMID 28496416, 2017). "Elevated circulating levels and expression of MMP-9 have been associated with the development and progression of atherosclerosis, and the importance of the MMP-9 gene, especially the functional promoter −1562 C/T polymorphism, is documented in both experimental and clinical studies." (PMID 24040261, 2013). "Moreover, MMP-9 has been implicated in atherosclerosis and atherosclerotic plaque stains positive for MMP-9 by immunhistochemistry." (PMID 21698093, 2011). "At concentrations of 10 μg/mL and 50 μg/mL, MMP-9 expression was significantly elevated, suggesting that high-dose FN promotes inflammation and matrix degradation, which may exacerbate atherosclerosis and increase the risk of plaque instability in advanced stages." (PMID 40649979, 2025).
atherosclerosis (continued). "In addition, the inhibition of fibrin deposition by MMP-9 plays a role in the reduction of thrombus size and may be associated with a decrease in the progression of atherosclerosis." (PMID 33419373, 2020). "Matrix metalloproteinase-9 (MMP-9) is a zinc-dependent enzyme that degrades the extracellular matrix and is involved in various diseases, including rheumatoid arthritis, atherosclerosis, tumor invasion, and metastasis." (PMID 41701802, 2026). "As expected, all markers of ECM degeneration—Ki-67, Col3a1, and Mmp-9—had the highest expression in mice with advanced atherosclerosis (33-week-old group)." (PMID 40278373, 2025). "Compared to the control group, the Plut-treated group exhibited reduced CD68+ (macrophage) and MMP-9+ immunoreactive atherosclerosis, whereas the Dlut-treated group demonstrated the lowest macrophage infiltration and lowest MMP-9 expression among all cohorts." (PMID 40656542, 2025). "Interferon-β (IFN-β) can somewhat inhibit the progression of atherosclerosis by downregulating the mRNA expression of MMP-9." (PMID 40710369, 2025). "MMP9, once mainly studied in vascular remodeling and atherosclerosis, is increasingly recognized for its role in cholesterol metabolism and lipid homeostasis." (PMID 41304686, 2025). "MMP9 plays a significant role in vascular inflammation and plaque instability, making it a critical factor in cardiovascular disease, especially in atherosclerosis." (PMID 40142959, 2025). "MMP-9 significantly increases cardiovascular diseases such as hypertension, atherosclerosis, fibrosis, and myocardial infarction." (PMID 39388499, 2024). "In the current study, we have presented evidence for the direct involvement of MMP9 in the atherosclerosis process, and also correlated this with in vivo evidence from a mouse model of T2DM." (PMID 38660518, 2024). "MMP-9, a collagenase, plays a key role in extracellular remodeling, and is often involved in vascular pathologic processes such as atherosclerosis, endothelial mesenchymal transition, angiogenesis, permeability, and inflammation." (PMID 38390944, 2024). "Cytokines, including pentraxin 3 (PTX3), copeptin, lipoprotein(a) [Lp(a)], and matrix metalloproteinase-9 (MMP-9), influence atherosclerosis progression and plaque vulnerability." (PMID 38929525, 2024). "Osteopontin (OPN) and matrix metalloproteinase-9 (MMP-9) contribute to CAC and atherosclerosis progression, with MMP-9 enhancing macrophage infiltration and matrix degradation." (PMID 39518492, 2024). "In particular, PDGF-CC is reported to play important roles in atherosclerosis by stimulating the expression of matrix metalloproteinase (MMP)-9 and influencing monocyte migration and invasion in a concentration-dependent manner." (PMID 38273388, 2024). "In the current study, we investigated the role of MMP9 in the early development of atherosclerosis in diabetes." (PMID 38660518, 2024). "SP-8356 showed anti-atherosclerosis effects by inhibiting the cluster of differentiation 147 (CD147)/matrix metalloproteinase 9 (MMP9) pathway and anti-metastatic effects on breast and liver cancers by inhibiting the NF-κB signaling pathway." (PMID 39684478, 2024). "MMP9 correlated with left ventricular dysfunction after myocardial infarction, atherosclerosis coronary artery disease, and is increased by proinflammatory cytokines, such as interleukin-1 (IL-1), IL-6 and tumor necrosis factor α (TNFα)." (PMID 39273682, 2024). "Secondly, AKT1 and MMP9 are both enriched in multiple signaling pathways, such as Fluid shear stress and atherosclerosis, Lipid and atherosclerosis, AGE-RAGE signaling pathway in diabetic complications, and TNF signaling pathway." (PMID 38528143, 2024).
atherosclerosis (continued). "Another study analyzing atherosclerosis-associated biomarkers in T2DM females reported a decrease in MMP2 and MMP9 levels with an increase in GLP-1 and GLP-1R levels." (PMID 37686344, 2023). "The NGAL/MMP-9 complex allows leukocytes and cytokines to invade the intima and promotes the development of atherosclerosis." (PMID 37521280, 2023). "We identified 15 identical pathogenic genes, and four of which (MMP9, MMP12, CD36, and FABP4) were considered as the key target genes of atorvastatin in anti-atherosclerosis and NSCLC." (PMID 37978381, 2023). "On the other hand, harmful MMPs are present, such as MMP-9 which has been found to have altered expression in atherosclerosis." (PMID 36865918, 2023). "The expression of MMP-2 and MMP-9 is augmented in inflamed tissues during chronic inflammatory conditions, such as obesity, arthritis, atherosclerosis, and periodontal disease." (PMID 37658104, 2023). "Ang-2 and MMP-9 are considered markers of cardiovascular disease, atherosclerosis and endothelial dysfunction." (PMID 37509589, 2023). "For example, macrophages-derived MMP-9 promotes the infiltration of macrophages into the lesion, thereby promoting the progression in the early stage of atherosclerosis." (PMID 36683743, 2023). "It has been reported that MMP-9 is closely related to intracranial aneurysms, atherosclerosis, ischemic brain injury, and other diseases." (PMID 37475739, 2023). "Gene Expression Omnibus (GEO) validation demonstrated that VEGFA was downregulated, while MMP9 and IL-1β were upregulated in patients with atherosclerosis." (PMID 37880698, 2023). "The results were validated using ClueGo + Pedia apps, and the “Fluid shear stress and atherosclerosis” pathway, including the three genes (IL-1β, MMP9, VEGFA), were the target genes in the eight hub genes." (PMID 37880698, 2023). "HDL-bound-S1P was shown to inhibit inducible NO synthase (iNOS) and matrix metalloproteinase 9 (MMP9), both of which promote the inflammatory-related process of atherosclerosis in rat VSMCs." (PMID 37608809, 2023). "Dysregulation of MMP-9 plays a pertinent role in various pathophysiological processes, such as inflammation, atherosclerosis, central nervous system diseases, and autoimmune diseases." (PMID 37090698, 2023). "Studies are needed to further explore the mechanism of action of atorvastatin on MMP9 to effectively treat both atherosclerosis and NSCLC." (PMID 37978381, 2023). "Differentially expressed genes CCl3, Hsap5, Mmp9, Fos, Ctsk corresponded to rheumatoid arthritis, lipid and atherosclerosis, and the Toll-like receptor signaling pathway." (PMID 36445632, 2023). "MMP9 is a matrix metalloproteinase that is involved in various pathological processes, such as inflammation and atherosclerosis." (PMID 36212940, 2022). "To validate the effect of APT1 on the H-Ras downstream signaling pathways, we measured the expression of p-ERK and its downstream atherosclerosis-related factors, such as MMP-9, VCAM-1, and ICAM-1." (PMID 35455042, 2022). "Further research results show that the RAB5A, CTTN, ITGB11and MMP9 can be used to predict atherosclerosis which is verified by GSE28829 and GSE43292." (PMID 35059464, 2022). "Inhibition of the IκB/NF-κB signal pathway via the MMP9/TIMP1 axis has an effect on vascular inflammation T2DM atherosclerosis." (PMID 35990823, 2022). "Previous studies have demonstrated that macrophage-derived MMP9 promotes the infiltration of monocyte/macrophages into the lesions thereby enhancing atherosclerosis and NCF1 expression leads to priming of human macrophage oxidative burst." (PMID 36035208, 2022). "It suggests that NGAL/MMP-9 complexes are involved in vascular inflammation and reconstruction in atherosclerosis and MACCE." (PMID 36397150, 2022). "MMP2 and MMP9 are a kind of proteases that have been reported to mediate plaque rupture and inflammation in atherosclerosis." (PMID 35783840, 2022).
atherosclerosis (continued). "Previous studies have already shown that the change of MMP9 level in circulation is an independent predictor of atherosclerosis." (PMID 36064568, 2022). "MMP-9 has also shown to be significantly increased in the untreated atherosclerosis rats and showed a significant correlation with all measured parameters." (PMID 33571214, 2021). "In atherosclerosis, excessive matrix proteolysis mediated by matrix metalloproteinases (MMPs), particularly MMP-9, is thought to be a common and important stage in the development of lesions." (PMID 34829801, 2021). "Our group has showed Matrix Metalloproteinase 9 (MMP-9), as a proposed link between atherosclerosis and osteoporosis in atherosclerotic rat model." (PMID 34610044, 2021). "In the present study, we found that MMP3 and MMP9 secretion by platelets participates in atherosclerosis." (PMID 33728029, 2021). "Given the importance of inflammation, macrophage activation, and MMP9 activity in atherosclerosis pathogenesis, our data suggest a promising potential of CaD as an anti-atherosclerotic agent." (PMID 34829669, 2021). "Clinical as well as animal studies have confirmed that MMP-9 levels are increased in both peripheral blood and plaques in atherosclerosis, and the degree of increase is positively correlated with lesion severity." (PMID 34924986, 2021). "This study highlights the impact of MMP9 in early vascular calcification, as well as providing new ideas for improving prognosis in patients with atherosclerosis." (PMID 34938784, 2021). "Increases in circulating levels of MMP-9 occur in several metabolic syndromes such as type 2 diabetes (T2D) and cardiovascular diseases such as atherosclerosis." (PMID 34829801, 2021). "Our study also found that new genes like CSF2RB, IL1RN, CCL5, MMP9, CD53, NCF2 and TLR2 associated with Inflammation present high expression both in psoriasis and atherosclerosis." (PMID 34122426, 2021). "We also explored its correlation to bone turnover markers in order to illustrate MMP-9 as a probable molecular link tying the pathogenesis of atherosclerosis and osteoporosis." (PMID 33571214, 2021). "MMP-9 is a kind of matrix metalloproteinases (MMPs) closely related to the development of IS, which promotes embryo development, inflammation, atherosclerosis, and other biological functions." (PMID 33727944, 2021). "In fact, it was shown that patients with atherosclerosis who had high serum levels of MMP-9 had a high risk of developing CVD and carotid endothelial dysfunction, underlining the essential role played by MMP-9 in the inhibition of NO at the endothelial level." (PMID 33810003, 2021). "This has boosted our interest in identifying pharmacologic agents that through targeting MMP-9 can provide benefits in terms of slowing the progression of atherosclerosis and also can protect against deterioration of bone quality." (PMID 33571214, 2021). "The results obtained indicate the involvement of some MMPs, especially MMP-9, in the processes of calcification, which requires additional research on the role of MMPs in vascular calcification and atherosclerosis development." (PMID 34205079, 2021). "It is known that macrophages resident in human and experimental atherosclerosis co-localize with and release active matrix metalloproteinases (MMPs), including the gelatinase MMP9, which specializes in the digestion of basement membranes." (PMID 34829669, 2021). "In common, MMP-9 has been recognized as a marker of various inflammatory diseases, such as atherosclerosis, arthritis, and systemic lupus erythematosus." (PMID 33954178, 2021). "To conclude, the matrix metalloproteinase (MMP-9), responsible for degradation of collagen fibres, has been shown in the present work to be overexpressed in the aortic strips of atherosclerosis model." (PMID 33571214, 2021). "One proposed role of MMP-9 in atherosclerosis is promoting the migration of vascular smooth muscle cells through the internal elastic lamina." (PMID 33571214, 2021).
atherosclerosis (continued). "In conclusion, this study provided the first evidence that miR-491-5p that targets MMP-9 is a novel modulator in the growth and migration of hVSMCs, which are related to atherosclerosis." (PMID 33313408, 2020). "According to clinical observations, upregulation of MMP-9 exhibited a correlation with instability of the atherosclerosis plaque and premature CAD development." (PMID 32429880, 2020). "Doxycycline inhibits the expression and activity of MMP-9, and doxycycline treatment can significantly inhibit atherosclerosis development." (PMID 33082709, 2020). "According to the previous studies, IL-37 indeed affects MMP2 and MMP9 expressions in endometriosis, atherosclerosis, and human lung adenocarcinoma." (PMID 32733162, 2020). "The qRT-PCR results showed that the expression level of MMP-9 was higher in the plasma samples of the patients with atherosclerosis than in the control." (PMID 33313408, 2020). "MMP-9 is potentially involved in the pathogenesis and progression of obesity, atherosclerosis, cardiovascular disease, metabolic syndrome, and T2D, while the circulatory MMPs are potential biomarkers of cardiovascular disease in T2D patients." (PMID 32806763, 2020). "Several studies have shown that matrix metalloproteinase-9 (MMP-9) plays an important role in the process of atherosclerosis and heart remodeling." (PMID 33841529, 2020). "The level of pro-MMP-9 was reduced in the serum of Apoe−/−Nba2.Yaa mice, indicating an increase in the proteolysis of the pro-peptide MMP-9 in the serum of the Apoe−/−Nba2.Yaa mice in advanced atherosclerosis." (PMID 33110193, 2020). "Analysis of ETAR, SMA and MMP-9 mRNA expression during the diet-induced progression of atherosclerosis reveals marked differences between ApoE−/− and control animals." (PMID 33255872, 2020). "HDL‐bound S1P inhibits inducible NO synthase (iNOS) and matrix metalloproteinase 9 (MMP9), both of which take active part in the inflammatory process of atherosclerosis." (PMID 32803879, 2020). "It has also been reported that MMP-9 plays a role in atherosclerosis development, and both MMP-2 and MMP-9, along with growth factors and cytokines, play roles in the development of proteinuria, tubulointerstitial fibrosis, and kidney disease progression." (PMID 33419373, 2020). "Another substance related to CSAP is MMP-9, which had been confirmed to be associated with atherosclerosis, and the increased activity of MMP-9 was found in unstable plaques, suggesting that MMP-9 plays a key role in plaque rupture." (PMID 33110434, 2020). "In conclusion, macrophage‐derived MMP‐9 facilitates the infiltration of monocyte/macrophages into the lesions thereby enhancing the progression of atherosclerosis." (PMID 32126159, 2020). "Many subsequent studies have shown that MMP-9 is involved in the process of atherosclerosis development." (PMID 33082709, 2020). "Taken together, the results strongly indicated that miR-491-5p played an important role in hVSMC viability, apoptosis, and migration by targeting MMP-9 in atherosclerosis." (PMID 33313408, 2020). "Other studies have demonstrated that TLR4 gene silencing reduces the levels of MMP-9 in human aortic smooth muscle cells in the context of atherosclerosis." (PMID 32784904, 2020). "In this study, we revealed that the expression of MMP-9 was regulated by miR-491-5p, which provides a possible pathway for its involvement in atherosclerosis." (PMID 33313408, 2020). "Among the hub genes, TNF, PTPRC (also known as CD45), VCAM1, CD86 and MMP9 have been confirmed as inflammatory biomarkers of atherosclerosis." (PMID 32213192, 2020). "Both MMP-2 and MMP-9 are important members of the MMP family, and are also implicated with cell migration by medicating inflammatory cell infiltration in atherosclerosis." (PMID 32314783, 2020).